GPR180 (G protein-coupled receptor 180)
Synonyms: ITR
Tractability: Antibody: UniProt predicts a signal peptide or a membrane-spanning region. PROTAC: ubiquitination databases record sites on it; its protein half-life has been measured.
Gene: Protein-coding gene on chromosome 13 (94,601,857 to 94,634,661, forward strand). Ensembl gene ENSG00000152749.
Subcellular location: Membrane
Subcellular location (Human Protein Atlas): Vesicles; Nucleoplasm; Primary cilium
Gene Ontology:
Biological process: G protein-coupled receptor signaling pathway; response to pheromone
Cellular component: membrane
Genetic constraint (gnomAD): Loss-of-function variants: 45 observed, 42.63 expected, observed/expected ratio (o/e) 1.06, 90% interval 0.83 to 1.35. The upper end of that interval is the gene's LOEUF score, 1.35, which puts it in group 5 of 6, group 1 being the genes least tolerant of losing a copy. Missense variants: 482 observed, 469.85 expected, observed/expected ratio (o/e) 1.03, 90% interval 0.95 to 1.11. Synonymous variants: 185 observed, 175.91 expected, observed/expected ratio (o/e) 1.05, 90% interval 0.93 to 1.19.
Homologues: Orthologues: chimpanzee GPR180 (100% identical), macaque GPR180 (99% identical), dog GPR180 (95% identical), pig GPR180 (94% identical), guinea pig GPR180 (93% identical), rabbit GPR180 (90% identical), rat Gpr180 (88% identical), mouse Gpr180 (87% identical), tropical clawed frog gpr180 (63% identical), zebrafish GPR180 (43% identical), Drosophila melanogaster CG9304 (22% identical), Caenorhabditis elegans T04F8.2 (17% identical). Paralogues in human: TMEM145 (21% identical).
Diseases named in the same sentence as GPR180 in open-access papers:
GPR180 is named in the same sentence as 18 diseases in open-access papers, as found by Europe PMC text mining. Sharing a sentence is not in itself a finding about the gene and the disease. The quoted sentences say what the papers report.
dyslipidemia (2 papers, 2023). "Consistently, recent GWAS studies have indicated that SNPs in GPR180 may be associated with dyslipidemia." (PMID 37111058, 2023). "In this context, GPR180 could be a novel therapeutic target for fatty liver and dyslipidemia." (PMID 36726016, 2023).
fatty liver (2 papers, 2023). "Our results demonstrate that deficiency of GPR180 in the mouse liver significantly decreases adiposity and liver steatosis induced by a high-fat diet." (PMID 37111058, 2023). "The findings of this study suggest that GPR180 could be a potential novel drug target for the treatment of adiposity and liver steatosis." (PMID 37111058, 2023). "Hence, GPR180 might represent a novel drug target for intervention of adiposity and liver steatosis." (PMID 37111058, 2023). "In conclusion, our study demonstrates that Gpr180 knockdown in the mouse liver can significantly inhibit HFD-induced obesity and liver steatosis." (PMID 37111058, 2023).
hepatoblastoma (2 papers, 2018 to 2022). Hepatoblastoma (HB) is a malignant hepatic tumor and is the most common pediatric liver cancer. "Limited genome-wide methylation analysis by HM450 found that differentially methylated genes were involved with liver cell differentiation and cancer, and four tumor suppressor genes (GPR180, MST1R, OCIAD2, and PARP6) were potentially related to progression in hepatoblastomas." (PMID 36212481, 2022).
Obesity (2 papers, 2021 to 2023). Accumulation of substantial excess body fat. "Thus, GPR180 represents a potential drug target for the treatment of lipid disorders such as obesity and NAFLD." (PMID 37111058, 2023). "The expression of GPR180 in subcutaneous WAT was significantly lower in participants with obesity, independent of glycaemic control." (PMID 34880217, 2021).
hepatoma (1 paper, 2023). "Reduction of mTOR phosphorylation was also shown in Huh7 cells, a human hepatoma cell line, which were knocked down by GPR180 shRNA." (PMID 36726016, 2023).
hypertriglyceridemia (1 paper, 2023). A laboratory test result indicating elevated triglyceride concentration in the blood. "Recent genome-wide association studies (GWASs) also indicate that single nucleotide polymorphisms (SNPs) in GPR180 are related to hypertriglyceridemia." (PMID 37111058, 2023). "Single-nucleotide polymorphisms in G protein-coupled receptor 180 (GPR180) are associated with hypertriglyceridemia." (PMID 37111058, 2023).
Impaired glucose tolerance (1 paper, 2021). An abnormal resistance to glucose, i.e., a reduction in the ability to maintain glucose levels in the blood stream within normal limits following oral or intravenous administration of glucose. "Furthermore, adipocyte-specific Gpr180 knockout mice developed impaired glucose tolerance and showed significantly higher body weight gain when challenged with HFD." (PMID 34880217, 2021). "Importantly, mice lacking Gpr180 showed elevated fasting blood glucose levels and displayed impaired glucose tolerance, although fasting insulin levels were not altered." (PMID 34880217, 2021).
liver disease (1 paper, 2021). "When challenged with high-fat diet (HFD), Gpr180 knockout mice gained more weight and this was accompanied by higher fat mass accumulation, pronounced liver steatosis and increased plasma ALT activity indicating an early stage of liver disease." (PMID 34880217, 2021).
malaria (1 paper, 2022). Malaria is a serious and sometimes fatal disease caused by a parasite that commonly infects a certain type of mosquito which feeds on humans. "Together, we identified Plasmodium GPR180 as an important signal transducer during gametogenesis and a potential target for developing drugs or vaccines to block malaria transmission." (PMID 35404079, 2022). "In conclusion, this study identified GPR180 as an integral constituent of the signaling pathway during the gametogenesis of malaria parasites." (PMID 35404079, 2022). "Genetic complementation shows that the GPR180 ortholog from the human malaria parasite P. vivax was fully functional in P. berghei, indicating functional conservation of GPR180 in Plasmodium spp." (PMID 35404079, 2022). "Antibodies against the N-terminal fragments of GPR180 exhibited TB activity, supporting future efforts to refine Plasmodium GPR180 as a target for disrupting malaria transmission." (PMID 35404079, 2022). "We used the rodent malaria parasite P. berghei to study the function of GPR180 during development." (PMID 35404079, 2022). "However, similar to previously identified TBV candidates, the GPR180 antigen only induced incomplete blocking of malaria transmission (∼70% with the MAb)." (PMID 35404079, 2022).
osteosarcoma (1 paper, 2018). A usually aggressive malignant bone-forming mesenchymal neoplasm, predominantly affecting adolescents and young adults. "Based on previous studies, whether the gene GPR180 could have function in osteosarcoma by producing tumor suppressors and its concrete role in chemoresistance remained to be explored." (PMID 29850522, 2018).
steatosis (1 paper, 2023). Increased lipid within the cytoplasm of cells. "Although, further studies are required to clarify whether CTHRC1 acts as an agonist for GPR180 in the liver, the development of antagonists is needed for the treatment of steatosis." (PMID 36726016, 2023).
tumor (4 papers, 2018 to 2025). "Another research indicated that the four novel tumor suppressor candidates including GPR180, MST1R, OCIAD2, and PARP6 were potentially useful molecular markers for predicting poor prognosis in HB patients." (PMID 33312943, 2020).
infection (2 papers, 2022 to 2023). The state of being infected such as from the introduction of a foreign agent such as serum, vaccine, antigenic substance or organism. "Cluster eight genes (n = 884) contained genes such as the putative interferon-responsive gene GPR180, which was modestly induced at 4 hpi, decreased at 12 hpi, and then in association with most other active genes, exhibited an upward trend in transcription during the later stages of infection." (PMID 35458509, 2022).
GPR180 also shares sentences with these, for which no sentence is quoted: breast carcinoma (1 paper); cancer (1); liver steatosis (1); prediabetes (1); type 2 diabetes (1).